GINM1 (glycosylated integral membrane protein 1)
Synonyms: C6orf72; dJ12G14.2
Tractability: Antibody: UniProt predicts a signal peptide or a membrane-spanning region; the Human Protein Atlas places it where antibodies can reach. PROTAC: ubiquitination databases record sites on it; its protein half-life has been measured.
Gene: Protein-coding gene on chromosome 6 (149,566,206 to 149,591,748, forward strand). Ensembl gene ENSG00000055211.
Subcellular location: Membrane
Subcellular location (Human Protein Atlas): Nucleoli fibrillar center; Plasma membrane
Gene Ontology:
Molecular function: protein binding
Cellular component: membrane
Genetic constraint (gnomAD): Loss-of-function variants: 10 observed, 11.69 expected, observed/expected ratio (o/e) 0.86, 90% interval 0.53 to 1.45. The upper end of that interval is the gene's LOEUF score, 1.45, which puts it in group 5 of 6, group 1 being the genes least tolerant of losing a copy. Missense variants: 152 observed, 137.3 expected, observed/expected ratio (o/e) 1.11, 90% interval 0.97 to 1.27. Synonymous variants: 70 observed, 54.93 expected, observed/expected ratio (o/e) 1.27, 90% interval 1.05 to 1.55.
Homologues: Orthologues: chimpanzee GINM1 (99% identical), macaque GINM1 (97% identical), dog GINM1 (86% identical), pig GINM1 (86% identical), guinea pig GINM1 (79% identical), rat Ginm1 (73% identical), mouse Ginm1 (73% identical), rabbit GINM1 (72% identical), zebrafish ginm1 (28% identical).
Diseases named in the same sentence as GINM1 in open-access papers:
GINM1 is named in the same sentence as 6 diseases in open-access papers, as found by Europe PMC text mining. Sharing a sentence is not in itself a finding about the gene and the disease. The quoted sentences say what the papers report.
bladder cancer (3 papers, 2020 to 2025). "The N-glycosylation pattern of GINM1, linked to disease progression in bladder cancer, has not been previously associated with TGCTs to our knowledge." (PMID 39999848, 2025). "Further, we identified distinct N-glycosylation pattern of CD44, MGAM, and GINM1 between NMIBC and MIBC patients, which may be associated with disease progression in bladder cancer." (PMID 32922663, 2020).
sarcopenia (1 paper, 2024). Progressive decline in muscle mass due to aging which results in decreased functional capacity of muscles. "Consistently across the three outcomes, RXRA, MDM1, RBL2, KCNJ2, and ADHFE1 were identified as risk factors, while NMB, TECPR2, MGAT3, ECHDC2, and GINM1 were identified as protective factors, all with potential as biomarkers for sarcopenia progression." (PMID 39409102, 2024).
neoplastic disease (2 papers, 2023 to 2025). "Of note, seventeen of thirty-nine proteins are reported as urine biomarkers in different diseases, of which eight proteins (PEBP1, EPS8L2, SERPINA1, FGA, SPINT1, CD55, SPARC, and GINM1) are related to neoplastic disease in urine specimens." (PMID 36918772, 2023). "Additionally, immunohistochemistry revealed protein-level accumulation of two candidate genes, ARID3B and GINM1, in both precursor and tumor cells." (PMID 39999848, 2025). "Additionally, through immunohistochemistry, we demonstrated the protein-level accumulation of two candidate genes, ARID3B and GINM1, in both precursor and tumor cells." (PMID 39999848, 2025).
cancer (1 paper, 2020). A tumor composed of atypical neoplastic, often pleomorphic cells that invade other tissues. "We observed unique glycosylation of glycoprotein integral membrane 1 (GINM1) in NMIBC patients, however the role of this protein in cancer development or progression is not yet reported." (PMID 32922663, 2020).
GINM1 also shares sentences with these, for which no sentence is quoted: embryonal carcinoma (1 paper); seminoma (1).